SMAD3 (SMAD family member 3)
Diseases named in the same sentence as SMAD3 in open-access papers (continued):
Sharing a sentence is not in itself a finding about the gene and the disease.
Myocardial fibrosis (continued). "RSV effectively ameliorated myocardial fibrosis and improved cardiac function by regulating Sirt1/Smad3 deacetylation pathway in rat model with DCM." (PMID 35081907, 2022). "A role for SMAD-2 and SMAD-3 signaling in fibrosis has also been suggested in post-infarction myocardial fibrosis." (PMID 36232788, 2022). "Notch is able to reduce myocardial fibrosis by inhibiting the transmission of TGF-β1/Smad3 signals, reducing the production of ECM in myofibroblasts." (PMID 36293363, 2022). "We first determined activation of TGF‐β/Smad3 signalling as it is a key pathway leading to chronic heart failure with progressive myocardial fibrosis." (PMID 33733577, 2021). "An additional effect of empagliflozin demonstrated in this study is the reduction of myocardial fibrosis by inhibiting the TGF-Beta1/Smad3 signalling pathway." (PMID 33150520, 2021). "(2020) in a mouse hypertensive heart disease model showed that increasing Smad7 is expected to block Smad3-mediated myocardial fibrosis." (PMID 35036160, 2021). "Overall, hyperglycaemia up‐regulated miR‐21, followed by down‐regulation of its target SMAD7, which, in turn, enhanced the phosphorylation of SMAD2 and SMAD3, thereby promoting EndMT activation and myocardial fibrosis." (PMID 31680453, 2020). "Our findings suggested that SCE prevents myocardial fibrosis and adverse remodeling after MI with a novel mechanism of suppressing histone methylation of the Smad3 promoter and its transcription." (PMID 31275414, 2019). "Only Smad3 expression in cardiac tissue was significantly decreased by SCE administration, suggesting that SCE attenuated myocardial fibrosis after MI by inhibiting the expression of Smad3." (PMID 31275414, 2019). "Consistent with our observation, few studies have shown increased Smad3 expression in scleroderma skin, scleroderma fibroblasts, and postinfarction myocardial fibrosis." (PMID 26997760, 2016). "In the context of DCM, hyperglycemia can directly stimulate TGF‐β1 expression, leading to phosphorylation of Smad2 and Smad3 in the cytoplasm, which then translocate to the nucleus to induce transcription of fibrosis‐promoting genes, thereby participating in myocardial fibrosis." (PMID 41573701, 2026). "Smad7 has a myocardial protective effect, and its overexpression could reverse Smad3-mediated myocardial fibrosis and nuclear factor kappa B (NF-κB)-driven inflammation." (PMID 39021834, 2024). "Here, we also detected the protein levels of the TGFβ-Smad signaling pathway (TGFβR2, p-Smad2, and p-Smad3) and myocardial fibrosis markers (Col1α1, Col1, α-SMA) in fibroblasts after 10 ng/mL TGFβ plus miR-194-3p mimic, miR-194-3p inhibitor and TGFβR2 siRNA treatment." (PMID 39346544, 2024). "Thus, increased expressions of SMAD2 and SMAD3 contributed to myocardial fibrosis in patients with HOCM, which happened early in childhood and continued through adulthood." (PMID 36878974, 2023). "Smad3 is the key downstream mediator of the TGF-β1 signaling pathway in myocardial fibrosis." (PMID 37465345, 2023). "Relevant data have indicated that suppression of the TGF-β1/Smad3 signaling pathway could attenuate myocardial fibrosis to prevent the progression and development of HF." (PMID 37465345, 2023). "Smad3 is the foremost TGF-β1 signalling molecule contributing to myocardial fibrosis." (PMID 35586685, 2022). "Also, deletion of Smad3 gene decreased cardiomyocyte hypertrophy and myocardial fibrosis along with reduced myocardial oxidative stress, leading to improved cardiac compliance in mice." (PMID 35401218, 2022). "Studies have found that S100A4 (fibroblast-specific protein 1) is associated with myocardial fibrosis after myocardial infarction and is regulated by Smad3 in myocardial interstitial fibroblasts, promoting myocardial fibrosis in the mouse model induced by pressure overload." (PMID 34484396, 2021).
Myocardial fibrosis (continued). "Thus, empagliflozin reduces the severity of oxidative stress by activation of the Nrf2/ARE signalling pathway and reduces myocardial fibrosis by inhibiting the TGF-Beta1/Smad3 signalling pathway." (PMID 33150520, 2021). "When the TGF-Beta1/Smad3 signalling pathway is impeded, there has been shown to be a reduction in collagen synthesis in cardiac fibroblasts, a reduction in myocardial fibrosis and the prevention of adverse remodelling in cases of pathological overload or damage to the left ventricle." (PMID 33150520, 2021). "Rebalancing the Smad3‐dependent anti‐ and pro‐fibrogenetic miRNAs could be another mechanism through which deletion of Smad3 protects against myocardial fibrosis in Smad3 KO‐db/db mice." (PMID 33733577, 2021). "Activated Notch signaling and inhibited TGF-β1/Smad3 signaling could repress myocardial fibrosis after myocardial infarction (MI)." (PMID 34988135, 2021). "Thus, SCE attenuates myocardial fibrosis and adverse remodeling after MI by suppressing histone methylation of the Smad3 promoter and Smad3 transcription." (PMID 31275414, 2019). "In addition, previous studies also suggested that the activation of Smad3 was essential for pressure overload or AngII-induced myocardial fibrosis." (PMID 28091697, 2017). "However, Smad3 KO mice subjected to transverse aortic constriction develop cardiac hypertrophy, although there is less myocardial fibrosis." (PMID 29073282, 2017). "To prove whether BMP-2 inhibition promoted TGF-β1-mediated fibrotic signalling pathway, we examined TGF-β1-induced activation of PKC-δ and Smad3, two important signal molecules that induced myocardial fibrosis, after knocking down BMP-2 in cardiomyocytes." (PMID 22283839, 2012). "The stimulation of CB2 signaling by AM1241 diminished the development of myocardial fibrosis during the post-myocardial infarction phase via enhancing the translocation of the fibrogenesis-associated transcription factor Nrf2 to the nucleus and blocking the TGF-β1/Smad3 pathway." (PMID 35413977, 2022). "Thus Sirt1/Smad3 deacetylation pathway may also be involved in the development of myocardial fibrosis." (PMID 35081907, 2022). "QL down-regulates the TGF-β1/Smad3 signaling pathway through inhibition of the NLRP3 inflammatory vesicle, thereby suppressing myocardial inflammation and myocardial fibrosis." (PMID 40881586, 2025). "QL:reducte in myocardial fibrosis, promote TGF-β3/Smad7, and inhibite TGF-β1/Smad3;reverse Bax/Bcl-2 upregulation;inhibite Smad3 by upregulating miR-345-3p." (PMID 40881586, 2025). "In the heart failure mouse model and SIRT3 knockout mouse model, 2-APQC inhibited myocardial hypertrophy and relieved myocardial fibrosis by regulating the AKT-mTOR and TGF-β-Smad3 signaling pathways through SIRT3 activation." (PMID 38744811, 2024). "Overall, besides of positive regulation to myocardial fibrosis by increased expression of SMAD2 and SMAD3, decreased expression of SMAD7 was closely related to collagen deposition, which negatively expedited fibrotic responses in patients with HOCM." (PMID 36878974, 2023). "To verify the involvement of Smad3 in FAT10-mediated myocardial fibrosis, we first examined the effects of FAT10 on Smad3 expression." (PMID 36778114, 2023). "It has been reported that simvastatin improved myocardial fibrosis in rats with MI by down-regulating TGF-β1 and downstream SMAD3 expression and up-regulating SMAD7 expression." (PMID 35498008, 2022). "Briefly, our study substantiated that myocardial fibrosis induced by pressure overload, was attenuated by PFD via repressing TGF‐β1/Smad3 signalling." (PMID 35861038, 2022). "In the present study, we clarified that TRIM33 attenuated Ang II–induced myocardial fibrosis in vivo and in vitro by mediating TGF-β1/Smad3/4 signaling and that the effect of TRIM33 was regulated by HSPB5." (PMID 35333698, 2022).
Myocardial fibrosis (continued). "Collectively, PFD attenuates myocardial fibrosis and dysfunction induced by pressure overload via inhibiting the activation of TGF‐β1/Smad3 signalling pathway." (PMID 35861038, 2022). "Empagliflozin administered early after myocardial infarction reduce myocardial fibrosis and inhibit the TGF-β1/Smad3 fibrotic pathway, probably prior to exerting any hemodynamic or physiological effect." (PMID 34215277, 2021). "RAS-RH treatment appears to ameliorate X-ray-induced myocardial fibrosis via downregulation of TGF-β1, Smad3, and COL1α and via upregulation of microRNA-200a." (PMID 32382291, 2020). "Discussion and Conclusions: The beneficial effects of QL on DOX-induced CHF in rats are mediated by reduction in myocardial fibrosis, promotion of TGF-β3/Smad7, and inhibition of TGF-β1/Smad3." (PMID 32429724, 2020). "Ang II infusion significantly increased myocardial fibrosis, expression of collagen I, collagen III, and TGF-β1, as well as TGF-β1 downstream proteins p-Smad2, p-Smad3, TRAF6, and p-TAK1 (all p<0.05)." (PMID 30175152, 2018). "Specifically, SR-717 administration aggravated cardiac insufficiency in DOX-treated GsdmeCKO mice, and the attenuation of myocardial fibrosis, collagen deposition, and abnormal TGF-β/SMAD2/SMAD3 activation in DOX-treated GsdmeCKO mice was suppressed by SR-717 administration." (PMID 41208882, 2025). "Another study showed that Salvia miltiorrhiza and Carthamus tinctorius extract (SCE) effectively reduced myocardial fibrosis and inflammation by inhibiting H3K4me3 and H3K36 trimethylation (H3K36me3) at the Smad3 promoter in cardiac fibroblasts, leading to decreased Smad3 transcription." (PMID 37965091, 2023). "An animal study indicated that TGF-β1 and phosphorylated Smad3 were elevated in myocardial infarction rats and blocking the TGF-β1/Smad3 axis could restore cardiac function and mitigate myocardial fibrosis." (PMID 37465345, 2023). "Resveratrol can upregulate the level of SIRT3 in cardiac fibroblasts, inhibit the transformation of fibroblasts into myoblasts, inhibit collagen deposition, inhibit myocardial fibrosis and cardiac remodeling, and improve cardiac function by downregulating TGF-β/Smad3 pathway." (PMID 36120366, 2022). "Also, expressions of TGF-β1 and p-Smad3 were augmented, suggesting that the TGF-β1/Smad3 signalling pathway was involved in the process of myocardial fibrosis." (PMID 33535854, 2021). "MiR-1305 and miR-587 were found to regulate the expression of TGF-β pathway members related to virus infections and lymphocytes T activation, Mothers Against DPP Family Members - SMAD3, and SMAD4), ventricular remodeling, myocardial fibrosis and hypertrophy and, as a result, HF progression." (PMID 33233425, 2020). "Furthermore, TGFβ mediates apoptosis and promotes myocardial fibrosis through epithelial and endothelial cell trans-differentiation to mesenchymal cells, and enhances ECM synthesis through Smad3 dependent pathways." (PMID 30312306, 2018). "In this study, we assessed the hypothesis that Smad3 signaling and miR-29b mediate the effect of carvedilol on attenuating AMI-induced myocardial fibrosis in rat." (PMID 24086569, 2013). "This SGLT2i mechanism of action is particularly interesting, as it has been well documented in animal studies, that inhibition of the TGF-Beta1/Smad3 signalling pathway significantly inhibits myocardial fibrosis and left ventricular remodelling in HF regardless of the presence of diabetes." (PMID 33150520, 2021). "mRNA and protein levels of TGF-β1 are increased in myocardial-infarction scars and correlate with increased expression of collagen I and Smad3 phosphorylation, suggesting that activation of the TGF-β1/Smad3 signaling pathway may contribute significantly to myocardial fibrosis." (PMID 30713572, 2019).
Myocardial fibrosis (continued). "Thus, the cardioprotection of SFI treatment in CHF for myocardial fibrosis may be achieved by upregulation of Smad7 and downregulation of TGF-β1, Smad2, and Smad3 gene expression via TGF-β/Smads signaling pathway." (PMID 28698735, 2017). "Infiltration of monocytes is a significant episode in the initiation of myocardial fibrosis, because the monocytes may differentiate into macrophages and participate in the healing process through production of growth factors, such as TGF-β and Smad-3." (PMID 24171042, 2013).
asthma (70 papers, 2012 to 2026). "Only one intronic variant in SMAD3 was associated with asthma at a Bonferroni-corrected threshold (rs17293632, OR 1.80, 95%CI 1.28-2.54, P = 0.0008)." (PMID 42316380, 2026). "There is significant literature associating genetic/epigenetic variations in TGFB1 and its downstream signalling pathway (SMAD3) to asthma and atopy and heightened susceptibility of allergic disease." (PMID 37438758, 2023). "Genome-wide association studies similarly noted an association between single-nucleotide polymorphisms in the Smad3 gene and asthma risk." (PMID 37814791, 2023). "The hypermethylation of the SMAD3 gene promoter is associated with asthma, particularly in children of asthmatic mothers." (PMID 38043345, 2023). "Remarkably, an epigenome-wide association study (EWAS) on asthma also reported differential methylation of inflammatory response–related genes, including SMAD3." (PMID 33593334, 2021). "miR-19a has been found to enhance airway epithelial proliferation as result of the loss of TGFBR2-mediated SMAD3 phosphorylation in ASMCs from patients with severe asthma." (PMID 32714925, 2020). "eQTL analysis suggests that the TGFBR1 variant acts through gain of function and together with an intronic variant in a downstream gene, SMAD3, points to defective TGFβR1 signaling as one of the biological perturbations increasing asthma risk." (PMID 31959851, 2020). "SMAD3 has a predicted drug target and SNPs in SMAD3 are significantly associated with asthma in GWAS42,59." (PMID 30061609, 2018). "Transcriptional activation of GLI2 depends on SMAD3, which was one of the top asthma-associated genes in the original GABRIEL study." (PMID 27387956, 2016). "Fifty percent of SMAD3 mutation carriers suffered of allergic disease, especially asthma (23%) and allergic conjunctivitis (23%)." (PMID 24804794, 2014). "SMAD3 is a well‐replicated asthma risk gene, and a master regulator of TGF‐β‐dependent signalling." (PMID 36073598, 2022). "Further, TGFβ1 was identified as a putative driver of the molecular changes specific to IRF7lo viral asthma exacerbations, and recent transcriptomic analyses of nasal epithelium confirms a SMAD3-centered molecular signature associated with both viral and non-viral asthma exacerbations in children." (PMID 34367159, 2021). "Notably, TGFBR1 and SMAD3, which mediate TGFβ signalling, are susceptibility loci identified in GWAS for asthma." (PMID 32887352, 2020). "SMAD3, with SNP rs744910 located on chromosome 15, is another asthma susceptibility gene." (PMID 27658857, 2016). "Moreover, enhanced production of the proinflammatory cytokine IL-1β following bacterial lipopolysaccharide (LPS) activation of cord blood was observed in individuals at risk of childhood-onset asthma, in association with increased SMAD3 methylation and maternal asthma status." (PMID 35990635, 2022). "Several loci previously associated with childhood asthma (e.g., 15q22.33, 16p12.1, and 3q21.3 near genes SMAD3, IL4R, EEFSEC, respectively) were also linked here with a more generally selected asthma." (PMID 41213931, 2025). "Functional gastrointestinal disorders (FGID) studies have shown that genes related to asthma, such as DENND1B, SMAD3, SLC22A4/5 (5q31/IBD5), and ORMDL3, have been co-associated with Crohn's disease and ulcerative colitis." (PMID 37656879, 2023). "Transforming growth factor- β1(TGF-β1) induces EMT in lower airways via Smad3, leading to asthma or chronic obstructive pulmonary disease." (PMID 36984551, 2023). "In human studies, Smad3 hypermethylation was the strongest predictor of childhood asthma in children born to mothers with asthma in three birth cohorts." (PMID 37814791, 2023). "IBD and asthma also share susceptibility genes, including gene loci DENND1B, SMAD3, SLC22A4/5 (5q31/IBD5) and ORMDL3 gene variants." (PMID 37835065, 2023).